CALD1 (caldesmon 1)
Diseases named in the same sentence as CALD1 in open-access papers (continued):
Sharing a sentence is not in itself a finding about the gene and the disease.
cancer (33 papers, 2009 to 2025). A tumor composed of atypical neoplastic, often pleomorphic cells that invade other tissues. "Using Gene Set Enrichment Analysis (GSEA), the KEGG pathway indicated that CALD1 and its related genes were primarily associated with Proteoglycans in cancer, Cell adhesion molecules (CAMS), PI3K-Akt signaling pathway, Ribosome, Spliceosome, Proteasome, etc.." (PMID 38365611, 2024). "ERK1/2 is known to drive cancer via downstream signaling, whereas CALD1 is associated with actin." (PMID 39776493, 2024). "We confirmed the differential upregulation of previously known genes in such as SCIN, CALD1 and MCAM, which have been associated with aggressive, basal-like phenotype and in acquired drug resistance in cancer." (PMID 40946111, 2025). "CALD1 was originally considered to be a smooth muscle marker, but it has also been recognized as having a role in the progression of some cancers." (PMID 40430098, 2025). "Actually, these results are supported by previous findings that CALD1 inhibits cancer cell metastasis." (PMID 36230524, 2022). "l-CALD1 can be a biomarker for the pathological diagnosis of cancers because the upregulated expression of l-CALD1 has been observed in different cancer types." (PMID 34070840, 2021). "Analogously, CALD1 expression is elevated in normal tissue of other cancer types." (PMID 38365611, 2024). "This indicates that CALD1 is likely to be involved in cancer cell invasion and metastasis." (PMID 38365611, 2024). "Thus, based on our ground-truth dataset, the buffering capacity of the NAMPT and CALD1 gene pair in different tissue/cell types can be used to predict patient survival for specific cancer types." (PMID 35194081, 2022). "Additionally, the predictive value of CALD1 in cancer progression was confirmed through the ROC curve with an AUC of 0.679." (PMID 34051818, 2021). "The mis-splicing of CALD1 was an independent epigenetic event that was related to the destruction of the tight junctions between epithelial cells, hence altering the stiffness of the extracellular matrix and promoting cancer invasion and metastasis." (PMID 34051818, 2021). "Furthermore, the proliferation, invasion, and migration abilities of cancer cells were suppressed after reducing CALD1 expression in CRC cell lines." (PMID 33996905, 2021). "Concerning CALD1 (caldesmon), this protein seems to display contradictory roles in cancer." (PMID 29681787, 2018). "However, the precise role of CALD1 in various cancers remains a subject of controversy." (PMID 38365611, 2024). "The treatment of cancer cells with DBMSCs in the IC setting modulated the expression of various factors with a specific role in cellular adhesion, including AKT1, CALD1, CDH1, FN1, and STAT3." (PMID 39768220, 2024). "Odds ratios were calculated, and the biomarkers that showed significant difference between Non-cancer and CaP were free/total PSA (p = 0.003), TARDBP (p<0.001), TLN1 (p = 0.006) and CALD1 (p<0.001)." (PMID 31404106, 2019). "Among these proteins, we have identified many differentially abundant proteins identified as having a role in cancer (IFIT1, FASTKD2, PIP4K2B, ARID1B, SLC25A33: overexpressed in TR; CALD1, CPA3, B3GALT5, CD177, RIPK1: overexpressed in NR)." (PMID 29681787, 2018). "Similarly, several effector molecules, including CALD1, CDH1, FN1, FZD7, RAC1, STAT3, and WNT11, were downregulated in cancer cells treated with DBMSCs." (PMID 39768220, 2024).
cancer (continued). "Other identified common up-regulated hub genes such as AKAP12, WFDC2, CALD1, and VSNL1 are related to drug resistance in various cancers although their involvement in oxaliplatin resistance in CRC was not identified and can be reported as protentional biomarkers which merits further exploration." (PMID 37535601, 2023). "For immune-related genes, the expression of genes involved in the categories of tight junction such as MYH11, PPP2R2C, and MYL9, cancer development such as TAGLN and CALD1, and acquired immunity such as PCP4 and CXCL13 was upregulated in the LP group when compared with that in the CON group." (PMID 37731924, 2023). "Further studies on CALD1 may provide insights into the immune network in BLCA and offer new targets for cancer treatment." (PMID 34051818, 2021). "Additionally, 11 step-changing proteins (including KRT families, PRDX2, CALD1, and others) were decreased in the IBC tissues compared with both cancer-adjacent and normal." (PMID 33194682, 2020). "We have identified many differentially abundant proteins already identified as having a role in cancer, such as the earlier discussed proteins IFIT1, FASTKD2, PIP4K2B, ARID1B and SLC25A33 (more abundant in TR) or CALD1, CPA3, B3GALT5, CD177 and RIPK1 (more abundant in NR)." (PMID 29681787, 2018). "Furthermore, the study observed a trend of increasing CALD1 level with cancer metastasis, although no statistical significance was obtained." (PMID 34051818, 2021). "In this current study, several CAFGs—VIM, ANXA1, HOPX, CALD1, and COL8A1—were confirmed highly expressed in TC cells, but not in those of other cancers (except ANXA1 in PDAC)." (PMID 41228323, 2025).
gastrointestinal tumors (1 paper, 2023). "Furthermore, non-canonical PTMs including GLUT1-associated lncRNAs regulated SUMOylation of GLUT1 protein, PRL-3 isoprenylation mediated translocation, and succinylated CALD1 protein lead to metastasis of gastrointestinal tumors." (PMID 37777749, 2023).
CALD1 also shares sentences with these, for which no sentence is quoted: Malignant Melanomas (3 papers); acute myeloid leukemia (1); age-related macular degeneration (1); amyloidosis (1); B-cell lymphoma (1); cancer of the blood (1); carcinoid tumor (1); colorectal adenocarcinoma (1); diabetic retinopathy (1); esophageal cancer (1); gastric tumors (1); glioblastoma multiforme (1); head and neck cancer (1); Hiatus hernia (1); Hodgkins lymphoma (1); Huntington disease (1); idiopathic pulmonary fibrosis (1); infection (1); influenza (1); ischemia (1); leukemia (1); liposarcoma (1); liver cirrhosis (1); liver diseases (1); lymphoma (1); myeloma (1); orofacial cleft (1); osteosarcoma (1); ovarian mucinous cystadenocarcinoma (1); ovarian tumor (1).
A further 8 diseases each share a sentence with CALD1 in 1 paper.